ALK (ALK receptor tyrosine kinase)
Diseases named in the same sentence as ALK in open-access papers (continued):
Sharing a sentence is not in itself a finding about the gene and the disease.
glioma (continued). "An ALK (Anaplastic Lymphoma Kinase) gene fusion has also been described in rare cases of gliomas, resulting in the activation of similar pathways." (PMID 34572171, 2021). "Although gliomas with ALK fusion are rare and the published literature is limited to several case studies, CCDC88A-ALK and PPP1CB-ALK were reported as the most frequent alterations." (PMID 33673070, 2021). "Despite the frequency of ALK alterations in pediatric cancer, reports of its presence in glioma are rare and often exist in isolated case reports." (PMID 32164789, 2020). "Recently, ALK alterations were shown to form a unique clinical subgroup of infantile glioma that require would likely benefit from a refined treatment approach." (PMID 32164789, 2020). "iNHAs overexpressing CCDC88A-ALK or PPP1CB-ALK were tumorigenic in vivo with 100% penetrance, forming glial tumors with a high MIB-1 proliferative index, pseudopalisading necrosis, focal GFAP expression, lack of synaptophysin expression and ALK overexpression." (PMID 31554817, 2019). "In implanted murine gliomas with production of pleiotrophin that acts as an upstream regulator of ALK signaling, treatment with an ALK inhibitor reduced vascular density and decreased vascular diameter." (PMID 28837676, 2017). "It has been implied that ALK contributes to gliomagenesis via multiple mechanisms including growth stimulation, mediation of anti-apoptotic pathways, self-renewal of glioma stem cells, and angiogenesis." (PMID 27579614, 2016). "PTN/ALK signaling has previously been shown to be required for maintenance of glioma initiating cells." (PMID 27806344, 2016). "More recent studies show that MK contributes to glioma progression through ALK signaling and thus renders glioma cells resistant to antitumoral effects of cannabinoids." (PMID 23267434, 2012). "Importantly, in pediatric gliomas, gene fusions involving anaplastic lymphoma kinase (ALK), ROS proto-oncogene 1 (ROS1), neurotrophic tyrosine receptor kinase (NTRK2) and MET define a distinct, hemispheric high-grade subgroup with intermediate prognosis." (PMID 41514664, 2026). "While some ALK inhibitors have been shown to cause cell death in glioblastoma cell lines, there are no definite clinical studies of ALK inhibitors for gliomas." (PMID 41007824, 2025). "Consequently, the effectiveness of treatments targeting ALK is considered limited for gliomas, glioneuronal and neuronal tumors in adults, and in the majority of CNS tumors found in children (ESCAT IIIA)." (PMID 38339401, 2024). "Notably, crizotinib can suppress the MDK/ALK axis and effectively enhance the response of glioma-initiating cells (GIC) to TMZ in vitro and using GIC-derived xenograft models." (PMID 38334610, 2024). "Additionally, the classification now recognizes infant-type hemispheric glioma as a separate high-grade glioma category characterized by a unique molecular profile, including fusion genes involving ALK, ROS1, NTRK1/2/3, or MET, predominantly seen in newborns and infants." (PMID 38137148, 2023). "Furthermore, glioma patients with a higher expression of PTN or ALK have shorter survival times." (PMID 27579614, 2016). "Recent reports suggest that ALK and its ligand, MIDKINE (MDK), promote the resistance of glioma cells to anticancer therapies such as TMZ." (PMID 38334610, 2024). "Tumors harboring NTRK, ALK, ROS1 and MET fusions have been classified in WHO CNS 5 under the umbrella term infant-type hemispheric gliomas due to their hemispheric predominance (96.7% of fusions)." (PMID 38525424, 2024).
glioma (continued). "These include “diffuse midline gliomas (H3 K27-altered)”, “diffuse hemispheric gliomas (H3 G34-mutant)”, “diffuse pediatric-type high-grade gliomas (H3-wildtype and IDH-wildtype)” and “infant type hemispheric gliomas (ALK, MET, NTRK 1/2/3 or ROS1 fusion)”." (PMID 38525424, 2024). "Fusions with receptor tyrosine kinase genes (such as ALK, ROS1, NTRK, and MET) are highly prevalent and preclinical studies show promising results for kinase inhibitors for this glioma type." (PMID 39273062, 2024). "Infant-type hemispheric glioma is commonly initiated by a fusion event involving a receptor tyrosine kinase (RTK) gene, such as NTRK1/2/3, ALK, ROS1, or MET." (PMID 39273062, 2024). "Occurring in newborns and infants, these glial tumors are characterized by a distinct molecular profile driven by kinase fusion genes involving the NTRK family, ALK, ROS1 or MET." (PMID 38902810, 2024). "Oncogenic fusions with receptor tyrosine kinase (RTK) genes NTRK, ALK, ROS or MET drive a subgroup of pHGG in infants (IHG, Infant-type hemispheric glioma)." (PMID 38849845, 2024). "More recently, we evaluated the expression of ALK and PTN mRNA in normal brain and 34 glial tumor tissues using in situ hybridization of serial sections of surgical specimen." (PMID 23267434, 2012). "Notably, NTRK- and ALK-driven tumors formed a cluster separate from MET- and ROS1-driven gliomas, indicating systematic differences between these two groups with similar oncokinases." (PMID 41381884, 2026). "Some of these gliomas feature alterations in genes such as ROS1, ALK, MET, and NTRK1–3." (PMID 41155159, 2025). "Recent advances yielded remarkable responses of NTRK or ALK fusion pHGG to selective inhibitors, especially in IHG, but there is currently no effective selective therapy demonstrated for MET fusion-positive glioma." (PMID 38849845, 2024). "In the CNS, MDK-dependent ALK signal transmission in glioma cells results in the activation of the Akt/mTOR1 axis, preventing autophagy-mediated cell death by tetrahydrocannabinol (THC), thereby contributing to the cannabinoid-resistance of gliomas." (PMID 38098484, 2023). "Lorlatinib, a third-generation ALK inhibitor with enhanced BBB penetration, has shown efficacy in several pediatric and adult malignancies, including in a child with ALK-fused infant-type hemispheric glioma (IHG)." (PMID 37781183, 2023). "An example of a changed diagnosis includes the re-classification of a pleomorphic xanthoastrocytoma (P2830) to an infant-type hemispheric glioma, generated by an intrachromosomal deletion on chromosome 2p adjoining exons 1–12 of the CCDC88A gene with ALK exons 20–29 reported previously." (PMID 35449451, 2022). "Moreover, the ctDNAs in the metastatic brain tumors included ALK and MDM2, and glioma-related ctDNAs included 1p/19q and MDM2 followed by frequencies of ERBB2, IDH1, CDKN2A, CDK4, PDGFRA, CCNE1, MET." (PMID 32973641, 2020). "In this study, we found that the mutant genes in the metastatic brain tumors included ALK, MDM2, ATM, BRCA1, FGFR1, and KRAS, and there were no glioma-related mutant genes (MGMT, IDH1, IDH2, 1p/19q, BRAF, and TERT)." (PMID 32973641, 2020).
non-Hodgkin lymphoma (58 papers, 2006 to 2025). Distinct from Hodgkin lymphoma both morphologically and biologically, non-Hodgkin lymphoma (NHL) is characterized by the absence of Reed-Sternberg cells, can occur at any age, and usually presents as a localized or generalized lymphadenopathy associated with fever and weight loss. "For example, the anaplastic lymphoma kinase (ALK) was first implicated in the pathogenesis of an aggressive type of non-Hodgkin’s lymphoma." (PMID 29056714, 2016). "In contrast to other aggressive non-Hodgkin lymphomas, the prognostic value of iPET in ALK-positive ALCL appears insufficiently defined." (PMID 40453056, 2024). "Anaplastic lymphoma kinase-positive large B-cell lymphoma (ALK+ LBCL) is a rare subtype of non-Hodgkin lymphoma." (PMID 37906510, 2023). "The anaplastic lymphoma kinase (ALK) gene was initially discovered in 1994 in non-Hodgkin’s lymphoma, as a result of a chromosomal translocation involving the nucleophosmin (NPM) gene that led to the formation of the NPM-ALK oncogenic fusion protein." (PMID 35884511, 2022). "The second target, ALK (anaplastic lymphoma kinase), was selected due to the presence of ALK fusion proteins in several cancer types (e.g., non-Hodgkin’s lymphoma)." (PMID 34209493, 2021). "Anaplastic lymphoma kinase (ALK) positive large B-cell lymphoma (ALK+ LBCL) is an extremely uncommon non-Hodgkin lymphoma (NHL) with a distinctive histomorphologic, immunophenotypic and cytogenetic profile." (PMID 34513457, 2021). "In this basket trial, the ALK inhibitor ensartinib is under assessment in patients with relapsed or refractory NB among other solid tumours, non-Hodgkin’s lymphoma and histiocytic disorders with genetic alteration of ALK or ROS1 (NCT03213652)." (PMID 29642598, 2018). "The ALK (anaplastic lymphoma kinase) gene rearrangement was originally identified in the context of a subtype of Non-Hodgkin lymphoma where ALK was fused to nucleophosmin (NPM) as a result of a chromosomal translocation." (PMID 26208325, 2015). "Anaplastic lymphoma kinase (ALK) was first discovered as a fusion gene with nucleophosmin in non-Hodgkin's lymphoma." (PMID 26678488, 2015). "Originally, truncated form of ALK was first described in non-Hodgkin's lymphoma with fusion protein product of ALK and nucleophosmin (NPM)." (PMID 25054154, 2014). "A truncated form of ALK was first described as part of a transforming chimeric protein in non-Hodgkin's lymphoma, in which ALK sequences were found to be fused to sequences of the nucleophosmin gene product (NPM)." (PMID 22347506, 2012). "Anaplastic large-cell lymphoma (ALCL) is a rare type of non-Hodgkin’s lymphoma (NHL) comprising four subtypes: anaplastic lymphoma kinase (ALK)-positive ALCL (ALK+ ALCL), ALK-negative ALCL (ALK− ALCL), primary cutaneous ALCL (pcALCL), and breast-implant-associated ALCL (BIA-ALCL)." (PMID 37894456, 2023). "Despite the recent advances in non-Hodgkin lymphoma (NHL) treatment, the management of ALK-ve/sALCL and especially the R/R disease remains a great challenge." (PMID 39846607, 2025). "ALK-positive anaplastic large-cell lymphoma (ALCL) accounts for 10-15% of pediatric non-Hodgkin lymphoma (NHL) cases." (PMID 29899875, 2018). "The anaplastic lymphoma kinase (ALK) gene was first identified in 1994, when it was found to be fused to nucleophosmin in a subtype of non-Hodgkin lymphoma." (PMID 36900362, 2023). "ALK+ and ALK- ALCL combined represent ~2% of all adult non-Hodgkin lymphomas and are the fourth most common TCL (~10%) after peripheral TCL, not otherwise specified (PTCL, NOS), mycoses fungoides, and angioimmunoblastic TCL." (PMID 34572893, 2021). "These are a sub-type of non-Hodgkin’s lymphomas that predominantly affect children and young adults and are characterized by the expression of the nucleophosmin (NPM)/ALK chimeric oncoprotein." (PMID 28771164, 2017).
non-Hodgkin lymphoma (continued). "ALK+ ALCL is characterized by chromosomal translocations involving ALK at chromosome 2p23 and resultant ALK expression, representing approximately 10–15% of pediatric/adolescent and ~3% of adult non-Hodgkin lymphomas." (PMID 40507248, 2025). "Anaplastic lymphoma kinase (ALK)-negative anaplastic large-cell lymphoma (ALCL) is a rare type of highly malignant, non-Hodgkin lymphoma." (PMID 29758012, 2018).
glioblastoma (53 papers, 2006 to 2026). The most malignant astrocytic tumor (WHO grade IV). "Approximately 60% of glioblastomas express ALK, but ALK fusion proteins and mutations occur in only 1%." (PMID 34063424, 2021). "In vitro, high expression of c-MYC and activation of the ERK1/2 pathway were associated with resistance against alectinib in ALK-expressing glioblastoma cells, and administration of a c-MYC inhibitor or MEK inhibitor was able to overcome TKI resistance and led to resensitization of resistant cells." (PMID 34063424, 2021). "Although its primary target is glioblastoma multiforme, other ALK inhibitors have also shown therapeutic potential." (PMID 41007824, 2025). "A single-chain antibody approach (svFC) targeting ALK’s ligand-binding domain has also been shown to be highly effective in inhibiting the in vivo growth of ALK-positive glioblastoma." (PMID 32059449, 2020). "Expression levels of 50 genes were significantly different between grade II/III astrocytomas and glioblastomas, whereas expression levels of only 1 gene (ALK) differed significantly between astrocytomas and oligodendrogliomas." (PMID 31747973, 2019). "We used the human U87MG glioblastoma cells that express PTN with human umbilical vein endothelial cells (HUVEC) that express ALK." (PMID 23267434, 2012). "We have previously shown that the ALK protein and mRNA are overexpressed in some tumors of glial origin and shown that ribozyme-mediated depletion of ALK mRNA from human U87MG glioblastoma cells resulted in apoptosis of xenograft tumors in mice." (PMID 23267434, 2012). "ALK fusions and amplifications have also been reported in glioblastoma." (PMID 37773318, 2023). "However, the increased levels of VGF observed in both ALKAL2‐ and ALK‐F1178S‐driven NB are of interest given a recent report that VGF expression in glioblastoma promotes tumour survival and growth." (PMID 33411331, 2021). "PTN15 promotes glioblastoma proliferation in an ALK-dependent fashion, whereas immobilized PTN18 promotes haptotactic migration of glioblastoma cells in an RPTPβ/ζ-dependent fashion, indicating that both ALK and RPTPβ/ζ may be important in this type tumor." (PMID 30427932, 2018). "Here we examined the functional role of the ALK gene in glioblastomas (GBMs)." (PMID 28837676, 2017). "Interestingly, we also identified pathways regulated by a combination of histone modifications, gain of H3K4me3, H3K36me3 and H3K27ac or loss of H3K27me3 respectively, including cellular response to stress and ALK signalling, for which a dysregulation has been described in glioblastoma." (PMID 39915814, 2025). "ALK can be overexpressed in 43%–70% of glioblastoma cases and may have biologic relevance." (PMID 37773318, 2023). "PTN may also act as a ligand of ALK to maintain the cancer stem cell phenotype of glioblastoma." (PMID 28969035, 2017). "This trial reports for the first time that the addition of crizotinib, an ALK, ROS1, and c-MET inhibitor, to standard RT and TMZ is safe and resulted in a promising efficacy for newly diagnosed patients with glioblastoma." (PMID 35625997, 2022). "The aim of this work was to study the targets of crizotinib: ALK, ROS1, and MET by using IHC, FISH, and direct sequencing in nine GSC lines derived from nine glioblastoma samples." (PMID 28960893, 2017). "In this study we investigated ALK, ROS1, and MET status in nine glioblastoma stem cell lines and tumors from which they arise." (PMID 28960893, 2017). "Unfortunately, this study was terminated early and since enrollment was only based on ALK positive immunohistochemistry, there is no data on types of ALK alterations included in the glioblastoma cohort available in public domain." (PMID 37773318, 2023).
glioblastoma (continued). "ALK overexpression, without ALK gene amplification or translocation, has been shown in human tumors and in glioblastoma stem cell lines (GSCs), and ALK signaling has been associated with GSC self-renewal and tumor survival." (PMID 29186933, 2017). "Overall, only the most aggressive, high grade tumors, i.e., GBM (glioblastoma multiforme) and anaplastic oligodendroglioma showed an increased expression of PTN and ALK mRNA relative to normal brain tissues, relative to adjacent brain tissues and relative to low grade tumors (p < 0.01)." (PMID 23267434, 2012). "Moreover, a phase Ib clinical trial has evaluated the combination of the ALK inhibitor crizotinib with standard therapy in newly diagnosed glioblastoma patients, suggesting that targeting the MDK‐ALK axis may offer a new therapeutic strategy to overcome drug resistance." (PMID 40468625, 2025). "It was discovered in a prior work that the ALK pathway includes the SOX4, Sta3, Akt, and N‐myc activities, which jointly facilitated cell proliferation and tumor neovascularization in nonhypoxic contexts in glioblastoma." (PMID 36987665, 2023).